CHRNA5 (cholinergic receptor nicotinic alpha 5 subunit)
Diseases named in the same sentence as CHRNA5 in open-access papers (continued):
Sharing a sentence is not in itself a finding about the gene and the disease.
lung carcinoma (continued). "The present study follows up on data reported by some researchers by examining CHRNA5 polymorphisms and lung cancer risk in the population, suggesting that genetic variation in CHRNA5 may affect susceptibility to lung cancer among smokers." (PMID 31342675, 2019). "So, we deduced that the polymorphisms of CHRNA5 may influence susceptibility to lung cancer among the Chinese populations." (PMID 31342675, 2019). "CHRNA5 has strong implications in its association with lung cancer." (PMID 29486777, 2018). "All four CHRNA5 regulatory polymorphisms (rs3841324, rs503464, rs55853698, and rs55781567) and the coding SNP rs16969968 that we investigated here have also been associated with lung cancer risk." (PMID 29196725, 2017). "SNPs in the CHRNA5-CHRNA3-CHRNB4 cluster of neotenic acetylcholine receptor subunit genes could affect individual lung cancer susceptibility directly by influencing mucosa repair or indirectly by impacting on smoking behavior." (PMID 26079375, 2015). "The 15q25.1 lung cancer susceptibility locus, containing CHRNA5, could modify lung cancer susceptibility and multiple smoking related phenotypes." (PMID 25329654, 2014). "In European descent, the del/del genotype has a 2.9-fold increase in CHRNA5 mRNA levels and significantly reduces the lung cancer risk in female Caucasian ever-smokers, while in Han Chinese the del/del genotype is associated with hypoactivity of the promoter and decreased transcription." (PMID 25329654, 2014). "There was a limited number of related mediation studies to evaluate the impact of smoking (number of cigarettes smoked per day or smoking pack-year) on the relationship between variants (especially rs1051730) in CHRNA5/A3/B4 and overall lung cancer or chronic obstructive pulmonary disease (COPD)." (PMID 25233467, 2014). "Importantly, several GWAS based on Caucasian populations have consistently identified 15q25 as lung cancer susceptibility region, which contains the nicotinic acetylcholine receptor subunit gene cluster, harboring CHRNA5, CHRNA3 and CHRNA4 genes." (PMID 23469231, 2013). "Genetic variants at the 15q25 CHRNA5-CHRNA3 locus have been shown to influence lung cancer risk however there is controversy as to whether variants have a direct carcinogenic effect on lung cancer risk or impact indirectly through smoking behavior." (PMID 21559498, 2011). "Similarly, in three of four lung cancer cell lines examined, rs3841324-[Δ] caused an ∼80% decrease in CHRNA5 promoter-derived luciferase activity." (PMID 21858091, 2011). "One of these susceptibility loci, rs16969968, a non-synonymous variant polymorphism located in the exon five of CHRNA5 15q25 resulting in a change in amino acid at residue 398th of CHRNA5 from Asp to Asn, has been identified by GWAS as a risk locus for lung cancer." (PMID 40143965, 2025). "SNPs near the CHRNA3-CHRNA5-CHRNB4 gene cluster showing strong associations with lung cancer risk, are in strong LD, and there is overlap among SNP test statistics assigned to these genes (i.e., the test statistic for the same SNP was assigned to both CHRNA5 and CHRNA3)." (PMID 22363742, 2012). "Silencing CHRNA5 was found to exert opposite effects compared to silencing CHRNA7 on cell migration in lung cancer cells." (PMID 41201200, 2025). "Contrary to theoretical expectation, transcriptionally activated RTEs affect genes with established tumour-promoting functions, including the common essential RNGTT and the lung cancer-promoting CHRNA5 genes." (PMID 40336011, 2025). "Qi Wang discovered that the HYKK (AGPHD1) gene interacts with the CHRNA5-CHRNA3-CHRNB4 cluster and is implicated in the risk of lung cancer development." (PMID 38834983, 2024). "Here, we established a prognosis prediction model based on DRGs using LASSO and Cox regression analysis and further screened a key gene in the model, CHRNA5, for functional analysis in lung cancer cells." (PMID 38840910, 2024).
lung carcinoma (continued). "CHRNA5 accelerates lung cancer progression via the MAPK and VEGF pathways, influences melanoma growth via Notch1 regulation, and promotes radioresistance in oral squamous cell carcinoma by modulating E2F transcription factors." (PMID 38840910, 2024). "CHRNA5, a member of the nicotinic acetylcholine receptor superfamily, is a key modulator of nicotine-dependent lung cancer and other malignancies." (PMID 38840910, 2024). "The CHRNA5 promoter harbours a binding site for STAT3, and nicotine induces the proliferation of lung cancer cells by enhancing CHRNA5 expression and activating the JAK2/STAT3 signalling cascade." (PMID 38879667, 2024). "Activation of CHRNA5 can enhance the migratory and invasive potential of nicotine-stimulated lung cancer, hepatocellular carcinoma and melanoma cells." (PMID 38879667, 2024). "Previous work has further shown a downregulation of junctional proteins such as ZO-1 and p120 after depletion of CHRNA5 in A549 lung cancer cells." (PMID 38063293, 2023). "A recent prospective cohort study found that the CHRNA5 AA genotype variant was independently associated not only with an increased risk of developing COPD and lung cancer, but also with increased smoking exposure, referred to as the ‘triple whammy effect’." (PMID 36769181, 2023). "Strong evidence was assigned to six variants, including CHRNA5 rs16969968 with COPD and lung cancer risk." (PMID 37372959, 2023). "Mendelian randomization analyses revealed that hypomethylation and lower expression of CHRNA5, which encodes a smoking-related nicotinic receptor, are causally linked to increased risk of COPD and lung cancer." (PMID 33752734, 2021). "Finally, the rs17408276 and rs951266 in the CHRNA5 gene were found in different genotype frequencies among groups; the rs17408276 variant moderates nicotine deprivation, a neural index of cognitive control, and was associated with increased lung cancer risk in African Americans." (PMID 34205269, 2021). "Using these genetic effects as instrumental variables in MR analyses, we identified a putatively causal role of DNA methylation of CHRNA5 in COPD and lung cancer." (PMID 33752734, 2021). "CHRNA5/CHRNA3/CHRNB4 gene cluster is located on chromosome 15q25.1 and was reported to be associated with risk of lung cancer." (PMID 29416783, 2018). "Previously CHRNA3/CHRNA5/CHRNB4 locus and nearby gene PSMA4 have been associated with increased risk of lung cancer." (PMID 30543688, 2018). "By transcriptomic profiling of MCF7 cells exposed to CHRNA5 RNAi, we identified significant changes in multiple cancer related pathways some of which were previously shown for A549 lung cancer cell line." (PMID 30543688, 2018). "For example, the transcription of CHRNA5 can be modulated by alcohol in human embryonic cells and in response to nicotine exposure in bronchial epithelial cell lines and in lung cancer." (PMID 30543688, 2018). "Genome-wide association studies (GWAS) have identified a susceptibility locus for human lung cancer at chromosome 15q24-25, which contains the CHRNA3, CHRNA5, and CHRNB4 genes encoding the α3, α5, and β4 subunits of nAChRs." (PMID 28878681, 2017). "Both types of tumors also share a transcriptional dysregulation of the three nAChR subunit genes grouped at the chromosomal locus (15q25.1) that predisposes to lung cancer; gene expression was reduced (CHRNA3) or increased (CHRNA5 and CHRNB4)." (PMID 28978081, 2017). "CHRNA3, CHRNA5, and CHRNB4 are subunits of the nicotinic acetylcholine receptor, which contribute to lung cancer risk." (PMID 29207642, 2017). "Given the association between the CHRNA3/CHRNA5/CHRNB4 locus and the risk of lung cancer, attempts have been made to elucidate the pathophysiological role of these three genes encoding α3, α5 and β4 nAChR subunits." (PMID 28978081, 2017).
lung carcinoma (continued). "Genome-wide association studies (GWAS) have identified a susceptibility locus for human lung cancer at chromosome 15q24-25, which contains CHRNA3, CHRNA5, and CHRNB4 genes encoding the α3, α5, and β4 subunits of nAChRs." (PMID 27228072, 2016). "The region on 15q25 contains the genes CHRNA3, CHRNA5, CHRNB4, AGPHD1, and IREB2, and numerous GWA have shown evidence of association of this region with COPD, emphysema, lung cancer, and smoking intensity." (PMID 26634245, 2015). "AGPHD1 gene is involved in CHRNA5-CHRNA3-CHRNB4 clusters and supposed to be associated with lung cancer risk." (PMID 26079375, 2015). "Many previous studies show that genetic variations of CHRNA5/A3/B4 relate to overall lung cancer, lung ADC, smoking quantities, and nicotine dependence." (PMID 25233467, 2014). "Two SNPs (rs1051730 and rs8034191, both with p<1×10−17) with strong LD in the regions of 15q25.1 containing CHRNA3, CHRNA5, and PSMA4 are strongly associated with lung cancer risk among ever smokers." (PMID 25233467, 2014). "Several GWAS have demonstrated that genetic variants in CHRNA5 and CHRNA3, located at the 15q25.1 lung cancer susceptibility locus, influence the risk of developing lung cancer in European and US populations." (PMID 25329654, 2014). "Lung cancer studies also demonstrated up-regulation of CHRNA5 mRNA expression in lung adenocarcinomas, compared to normal lung tissue." (PMID 24303001, 2013). "There is evidence that variants in the region are associated with decreased expression of CHRNA5 in the lungs and that CHRNA5 expression is higher in lung cancers favouring a direct role." (PMID 21559498, 2011). "Both genome-wide and candidate gene association studies have pointed to the CHRNA5-CHRNA3-CHRNB4 cluster of nAChR subunit genes as being important in the etiology of NA, lung cancer, peripheral artery disease and chronic obstructive pulmonary disease." (PMID 21858091, 2011). "Given their roles as nicotine receptors, CHRNA3 and CHRNA5 may explain associations with smoking‐related diseases like COPD and lung cancer." (PMID 41377765, 2025). "The CHRNA5-CHRNA3-CHRNB4 cluster encodes nicotinic acetylcholine receptor subunits primarily expressed in aspiratory epithelium, pneumonic neuroendocrine cells, and lung cancer cells." (PMID 38834983, 2024). "In this study, we found that CHRNA5 might function as an oncogene, as evidenced by its upregulation in lung cancer and its positive correlation with oncogene expression." (PMID 38840910, 2024). "At P < 0.05, we found that lower expression of CHRNA5 was associated with higher risk of lung cancer, but not for COPD." (PMID 33752734, 2021). "Therefore, in this study we aimed at determining the frequency of the SNPs (rs16969968 in CHRNA5, and rs1051730 in CHRNA3) and elucidating their possible role in risk for nicotine dependence and lung cancer among the Palestinian population." (PMID 29609626, 2018). "CHRNA5 is in the nicotinic acetylcholine region that has well-known associations with lung cancer and smoking, while PSMA4 is also associated with lung cancer." (PMID 29486777, 2018). "And the nicotinic cholinergic receptor gene CHRNA5-CHRNA3-CHRNB4 located on 15q25 can influence the risk of lung cancer by affecting the nicotine dependence and downstream signaling pathways which contribute to increaser risk of lung cancer." (PMID 29416783, 2018). "In deed, the expression of cyclin D1, cyclin E2, and cyclin D3 were downregulated in CHRNA5 shRNA transfected lung cancer cells, suggesting that the G0/G1 phase to S phase transition might be regulated by α5-nAChR through cell cyclins." (PMID 28878681, 2017). "Gene expression profiling, using PrimeView Human Gene Expression Array, identified 1,972 transcripts that were significantly differentially expressed (P < 0.01), in CHRNA5 knockdown A549 lung cancer cells compared with control (Datasets submitted to GEO datasets, with GEO accession: GSE101979)." (PMID 28878681, 2017).
lung carcinoma (continued). "CHRNA5-CHRNA3-CHRNB4, the nicotenic acetylcholine receptor subunits, encode proteins that form receptors expressed in neurons and other tissues, particularly respiratory epithelium, pulmonary neuroendocrine cells and lung cancer cells." (PMID 26079375, 2015). "SNPs in CHRNA5-CHRNA3-CHRNB4 could be able to influence the binding function, thus influence individual lung cancer risk." (PMID 26079375, 2015). "Apart from smoke exposure, genome-wide association studies (GWAS) has provided a strong evidence that tobacco-dependent lung cancer patients had a susceptibility region in chromosome 15q25.1, including some genes (CHRNB4, CHRNA3, and CHRNA5) that encode for nicotinic acetylcholine receptors." (PMID 25280560, 2014). "Because knockdown of CHRNA3 and CHRNA5 increased the proliferation, migration and calcium influx of lung cancer cell lines, as a result of compensatory increase of assembly of α7-nAChR on the cytoplasm membrane which had higher permeability to calcium in response to nicotine." (PMID 24621512, 2014). "While only the nAChR genes on 15q25.1 (CHRNA5, CHRNA3, CHRNB4) have been previously associated with lung cancer risk, there is strong biological rationale to believe that other nAChR genes may influence risk." (PMID 23232035, 2012). "While the SNP rs16969968 is a non-synonymous SNP causing the D398N substitution in CHRNA5 and while 398N causes decreased response to a nicotine agonist, a direct role of this variant in lung cancer biology has thus far not been shown." (PMID 21559498, 2011). "Another cluster of genes, specifically the CHRNA5-CHRNA3-CHRNB4 loci on chromosome 15, encode the nicotinic acetylcholine receptor (nAChR) subunits that are expressed on lung epithelial cells, and variants in this region have been associated with a heightened COPD and lung cancer risk." (PMID 36769181, 2023). "The transcription profile of CHRNA5 depleted MCF7 cells showed a significant positive correlation with that of A549 lung cancer cell line while exhibiting a negative association with the CHRNA5 co-expression profile obtained from Cancer Cell Line Encylopedia (CCLE)." (PMID 30543688, 2018). "The association between CHRNA5 risk variants and mortality in people with lung cancer reflects an individual’s lifetime exposure to tobacco smoke, and we would not expect an instrumental variable estimate using CHRNA5 to reflect the effect of current smoking on prognosis." (PMID 30002074, 2018). "The same applies to another three genes KLF6 (Krüppel-like zinc finger transcription factor), MSH5 (MutS protein homolog 5) and ACTA2 (Alpha-smooth muscle actin), which were also found to be associated with lung cancer by several previous GWASs, albeit not as prominently as CHRNA5 and TERT." (PMID 27323854, 2016). "Cross‐validated SNPs rs16969968/rs12914385, cis‐regulatory hubs for COPD–lung cancer pathogenesis, colocalized with ρ‐HESS‐identified regions, mechanistically linking dysregulation of PSMA4, IREB2, CHRNA3, and CHRNA5 to disease etiology." (PMID 41377765, 2025). "Mechanistically, CHRNA5 mediates the Stat3–Jab1–Csn5 and TGF-β1–Smad signalling pathways to promote the metastasis and EMT of lung cancer cells." (PMID 38879667, 2024). "The CHRNA5 promoter had four STAT3 response elements, and the interaction between CHRNA5 and STAT3 facilitates the nicotine-induced proliferation of lung cancer cells." (PMID 38879667, 2024). "CHRNA5-mediated Ca2+ influx was found to activate MAPK and VEGF signaling pathways, thereby contributing to tumor progression in lung cancer." (PMID 35214008, 2022).
lung carcinoma (continued). "The locus on chromosome 15q25.1, including the nicotinic acetylcholine receptors CHRNA3, CHRNA5 and CHRNB4, showed concordant effect direction between SCZ, lung cancer, and smoking behavior." (PMID 29330379, 2018). "Some studies have demonstrated that the cluster of human neuronal nicotinic receptor gene CHRNA5-CHRNA3-CHRNB4 (15q25.1) is related to drug-related behaviors and the development of lung cancer." (PMID 29416783, 2018). "Interestingly, in our studies, CHRNA5 rs3841324 combined variant genotypes (ins/del+del/del) had an increased NPC risk compared to ins allele homozygotes, which is inconsistent with the results for lung cancer in which the del allele was a protective factor for a Caucasian population." (PMID 25329654, 2014). "Therefore, there is an urgent need to investigate whether or not CHRNA5 rs3841324 is involved in susceptibility to smoking-associated cancers in addition to lung cancer." (PMID 25329654, 2014). "However, no studies have investigated the association between CHRNA5 rs3841324, which has been proven to have the highest association with CHRNA5 mRNA expression, and the risk of other smoking-associated cancers, except lung cancer." (PMID 25329654, 2014). "In lung cancer, we have detected the expression of several nAChR subunit genes, in particular CHRNA3, CHRNA5, and CHRNB4." (PMID 24062692, 2013). "The locus on chromosome 15q25.1 contains three genes that encode nicotinic acetylcholine receptor (nAChR) subunits (CHRNA3, CHRNA5, CHRNB4) whose involvement in tobacco addiction was suggested from studies conducted on larger lung cancer populations." (PMID 21966413, 2011). "In a never‐smoking Chinese population study, the association between rs17486278 in gene cluster CHRNA5‐CHRNA3‐CHRNB4 and nonsmall cell lung cancer (NSCLC) was not significant (Li, Bao, Xu, Bao, & Zhang, 2012)." (PMID 31342675, 2019). "Importantly, they have also identified downregulation of p63 after knockdown of CHRNA5 or CHRNA3, which offered an explanation for the resistance to apoptosis in CHRNA3 downregulated lung cancers." (PMID 26981122, 2016). "We chose and studied three SNPs based on the Genome-wide association study of our supervisor’s project team and focused on the association between CHRNA5-CHRNA3-CHRNB4 single nucleotide polymorphism rs6495309, rs1948 and rs8040868 and the risk of lung cancer in population, smokers and nonsmokers." (PMID 29416783, 2018). "Interestingly, they found CHRNA3, but not CHRNA5, is often hypermethylated and downregulated in cancer tissues, whereas a 30-fold upregulation of CHRNA5 expression is observed in lung cancers compared with the normal lung." (PMID 26981122, 2016).
chronic obstructive pulmonary disease (14 papers, 2011 to 2024). A chronic and progressive lung disorder characterized by the loss of elasticity of the bronchial tree and the air sacs, destruction of the air sacs wall, thickening of the bronchial wall, and mucous accumulation in the bronchial tree. "Nearby genes of interest include CHRNA3 and CHRNA5; variants in this locus are associated with chronic obstructive pulmonary disease and lung cancer." (PMID 35173190, 2022). "Genome-wide Association Studies identified a locus including a non-synonymous single nucleotide polymorphism in CHRNA5, rs16969968, encoding the nicotinic acetylcholine receptor α5 subunit, predisposing to both smoking and Chronic Obstructive Pulmonary Disease." (PMID 34737286, 2021).